BDNF (brain derived neurotrophic factor)
Diseases named in the same sentence as BDNF in open-access papers (continued):
Sharing a sentence is not in itself a finding about the gene and the disease.
depression (continued). "In addition, serum levels of BDNF in depressed patients are lower than those of control subjects, suggesting that BDNF could be a biological marker for depression (Hashimoto 2010; 2015a)." (PMID 27844095, 2017). "Aside from decreasing BDNF expression and function in the PFC, the hippocampus, and other depression-related structures, depression has been found to reduce the blood BDNF levels in affected patients." (PMID 28706741, 2017). "Thus, it is highly probable that the deficit in synaptic strength and plasticity, along with dysregulated BDNF–5-HT2A signaling, in ApoE4 carriers increases their risk of developing depression, which, in the presence of environmental stressors, can lead to the manifestation of clinical depression." (PMID 28934977, 2017). "The decrease in the BDNF protein level was significantly reversed by Lu AA33810, which had antidepressant-like effect in the present gliotoxin model of depression." (PMID 27975125, 2017). "Our findings are in accord with our previous observations concerning brain-derived neurotrophic factor (BDNF) in the ESPRIT population; with increased methylation observed in individuals with depression." (PMID 29070016, 2017). "The release of BDNF is essential for antidepressant effects of KET and remodeling of the PFC networks is compromised in rodent models of depression." (PMID 27933365, 2017). "We found that in the hippocampus of CUMS-induced mice, BDNF levels were significantly decreased, and the results of Y-maze and MWM test were shown that the cognition impairment along with the depression symptoms." (PMID 28761074, 2017). "Another research, done by a Canadian group found changes in levels of serotonin, pro-inflammatory cytokines, brain-derived neurotrophic factor (BDNF) and other transmitters in comorbid chronic pain, depression and sleep disruption." (PMID 26649857, 2017). "We also previously demonstrated that HMF administered s.c. exerted antidepressant-like effects in a CORT-induced depression-like mouse model, and suggested that the effects of HMF were due to its ability to induce BDNF." (PMID 29023414, 2017). "Thus, mTOR and BDNF pathway may be a link between zinc, depression and neural plasticity." (PMID 28299207, 2017). "In this study, berberine influenced the BDNF-eEF2 pathway in the hippocampus, and CREB signaling in the frontal cortex, leading to antidepressant effects in the ovariectomy model of depression." (PMID 28465511, 2017). "Taken together, this indicates that inflammation decreases BDNF in the hippocampus and PFC, but increases BDNF in the NAc, resulting in depression-like behavior in rodents." (PMID 27844095, 2017). "In conclusion, the present study suggests that elevated inflammatory response, especially pro-inflammatory cytokines, and reduced levels of BDNF in the PFC play key roles in individual differences of comorbid neuropathic pain and depression." (PMID 28600519, 2017). "The ability of PA to modulate changes in BDNF and PGC-1α is relevant for stress-induced depression given their interaction with neuroinflammatory and neuroplasticity pathways via alterations in tryptophan degradation and 5-HT1A receptor activation." (PMID 28928987, 2017). "In this study, both BDNF and GDNF decreased by 21 d stress, indicating that CUMS successfully induced depression in a mouse model." (PMID 28348623, 2017). "Serum levels of brain-derived neurotrophic factor (BDNF) are low in major depressive disorder (MDD), and were recently shown to decrease in chronic depression, but whether this is a trait or state marker of MDD remains unclear." (PMID 27070410, 2016). "In conclusion, our study demonstrated that not only is the Keap1-Nrf2 system crucial to the pathophysiology of depression, but that decreased BDNF-TrkB signaling in the PFC, CA3, and DG plays a role in the depression-like phenotype of Nrf2 KO mice." (PMID 27470577, 2016).
depression (continued). "In particular, altered levels of peripheral (serum) BDNF have been found in patients with depression, generalized anxiety disorder and PTSD, supporting BDNF's potential role as a biomarker for disease." (PMID 26586578, 2016). "Here, we measured serum BDNF (seBDNF) level in hypertensive patients (HT) and healthy controls (CONT) and its relation to affective temperaments, depression and anxiety scales, and arterial stiffness parameters." (PMID 27478486, 2016). "Reduced expression of BDNF in the hippocampus and cortical regions is a clear conjuncture for AUD and depression because these are critical target brain regions in both disorders." (PMID 28082989, 2016). "Emerging evidence implicates brain-derived neurotrophic factor (BDNF) and serotonin (5-HT) in the pathophysiology of depression and in the actions of antidepressant agents." (PMID 28119573, 2016). "Based on this evidence, it appears that a relationship does exist between depression and prognosis in SCLC and that the mechanism by which depression affects prognosis is achieved via the downregulation of BDNF expression." (PMID 27852063, 2016). "Taken together, these results provide evidence that BDNF led to a considerable increase in chemosensitivity of NCI-H69 cells, which was in turn regulated by depression status." (PMID 27852063, 2016). "For the first time, the present results demonstrate the antidepressant-like activity of magnesium in the OB animal model of depression and indicate the potential involvement of the AMPA/BDNF pathway in this activity." (PMID 25027582, 2015). "Consistent with changes in patients with major depressive disorder, we found that the mice with PSD had reduced levels of BDNF and monoamine neurotransmitters such as serotonin and dopamine in different brain regions." (PMID 26572587, 2015). "A recent study indicates that the moderator effects of BDNF Val66Met and 5-HTTLPR in the relation between childhood adversity and depression are independent." (PMID 26230319, 2015). "In summary, chronic TFF3 treatment normalized olfactory bulbectomy induced depressive-like behaviors by the regulation of the BDNF-ERK-CREB pathway in the hippocampal CA3, a brain area crucial for depression." (PMID 26633367, 2015). "In contrast to BDNF and S100B, serum NSE levels seem to be stable in depression suggesting mainly glial dysfunction." (PMID 26500502, 2015). "Another possible link might be the brain-derived neurotrophic factor (BDNF), a member of the neurotrophic factor family, which is not only associated with major depressive disorder, but its higher serum level is also connected to a decreased risk of cardiovascular disease and mortality." (PMID 26512294, 2015). "Recently, it has been widely accepted that brain-derived neurotrophic factor (BDNF) and cyclic Adenosine monophosphate (cAMP) response element-binding protein (CREB) play critical roles in the pathophysiology of depression." (PMID 25618406, 2015). "Levels of brain-derived neurotrophic factor (BDNF), a protein with a significant role in neurodevelopment, and the development of depression and anxiety, were found to be reduced in the hippocampus and amygdala." (PMID 25698977, 2015). "Brain-derived neurotrophic factor (BDNF), a peptide critical for axonal growth, neuronal survival, and synaptic plasticity, is an important regulator in the upstream pathway of ERK in depression." (PMID 26633367, 2015). "These preliminary results suggest that genetic (SNV) and epigenetic (DNA methylation) factors interactions in BDNF and eventually in OXTR genes are involved in the anxiety disorders/depression phenotype in older adults." (PMID 26175754, 2015). "Brain derived neurotrophic factor (BDNF), S100B and neuron specific enolase (NSE) are among the most studied biomarkers in affective disorders, in particular major depressive disorder." (PMID 26500502, 2015).
depression (continued). "While most patients with MDD have reduced serum BDNF levels, the patients with lower SD showed higher serum BDNF levels than other patients with MDD, suggesting that a depressive state is not linked with depression-related biological changes in these patients." (PMID 25885038, 2015). "Brain-derived neurotrophic factor (BDNF) and its receptor, tropomyosin-related kinase B (TrkB), signaling represent potential therapeutic targets for major depressive disorder." (PMID 25628381, 2014). "VGF is upregulated by both BDNF and 5-HT treatment, and VGF protein in the hippocampus is reduced in animals subjected to behavioral models of depression." (PMID 25542689, 2014). "Meanwhile, supplementation with Bifidobacterium appears to attenuate an exaggerated stress response and maintain adequate levels of the neuropeptide brain-derived neurotrophic factor (BDNF), levels of which are known to be low in depression." (PMID 24422720, 2014). "In this report, we examined the putative interaction of a set of 12 psychosocial adversities experienced during childhood in relation to the candidate genes BDNF and SLC6A4 on their impact on major depression in adolescence." (PMID 24683520, 2014). "This suggests that BDNF acts within the VTA-NAc pathway, inducing a depression-like phenotype, whereas it produces antidepressant-like effects in the hippocampus and PFC." (PMID 25628381, 2014). "Previous studies have reported that serum BDNF levels are reduced in AD, MCI, major depression disorder, and depressive symptoms." (PMID 24782766, 2014). "Our results indicated that 6 weeks of CUMS exposure induced significant depression-like behavior, with low 5-HT and NE levels, high TNF-α and IL-6 in brain and high hippocampal TNF-α, IL-6, P-NF-κBP65, and 5-HT2AR levels, and low BDNF expression levels." (PMID 25587342, 2014). "The brain-derived neurotrophic factor (BDNF) has received particular attention, since it is considered a relevant biomarker of depression and suicidal behavior, and a possible downstream target of a variety of antidepressant drugs." (PMID 25386150, 2014). "The subgroup with moderate-to-severe depression (n = 16) was reanalyzed after stratifying it into two subgroups according to LDAEP and BDNF values (dichotomized at the medians into low and high)." (PMID 24663244, 2014). "In conclusion, COR remarkably improved depression-like behavior in CUMS mice and its antidepressant activity is mediated, at least in part, by the upregulating BDNF and downregulating 5-HT2AR levels and inflammation in hippocampus." (PMID 25587342, 2014). "The following depression-related parameters were determined: plasma ACTH, plasma corticosterone, adrenal gland weight and hippocampal levels of brain-derived neurotrophic factor (BDNF)." (PMID 24138845, 2013). "Interestingly, the serum BDNF levels were increased following the treatment of antidepressant medications, suggesting that the serum BDNF levels could be as a surrogate biomarker for determining both the depression status and the efficacy of antidepressant treatment." (PMID 23704927, 2013). "In addition to being influenced by stressors, BDNF might also play a significant role in how individuals respond to stressors (behaviorally and physiologically) and might thus also contribute to whether these responses culminate in depression." (PMID 23675319, 2013). "A significant negative correlation was revealed (Pearson r = −0.427, P = 7.75E-05) between the serum BDNF levels and the SDS scores in all subjects (n = 80), including 40 patients with depression and 40 controls." (PMID 23704927, 2013). "We also assessed brain-derived neurotrophic factor (BDNF) based on its recognized role on anxiety and depression and the fact that it is reduced in the plasma of PTSD victims." (PMID 23483949, 2013).
depression (continued). "Pharmacological interventions targeting the neurochemical systems involving NPY, BDNF, CRH, and HPA axis, among others, are being investigated as potential treatments for depression and PTSD." (PMID 23422934, 2013). "Our results indicated that there were significant interactions of the T102C and A1438G SNPs in 5-HT2A receptor gene, Val66Met SNP in BDNF gene, and C-1019G SNP in 5-HT1A receptor gene with depression with abnormal humor." (PMID 24274373, 2013). "The upregulation of NGF, BDNF, GDNF, and other neurotrophic factors is considered for treatment of depression and neurodegenerative diseases." (PMID 23878590, 2013). "The current study tests whether the brain derived neurotrophic factor (BDNF) Val66Met variant and 5-HTTLPR, two of the most widely studied candidate polymorphisms, exhibit replicable associations to established cognitive and interpersonal endophenotypes of depression." (PMID 24312122, 2013). "Thus, a better understanding of the close interaction(s) between BDNF and PUFAs and their metabolites may pave way for the development of newer therapeutic strategies in diabetes mellitus, depression and other clinical conditions in which they are believed to play a significant role." (PMID 22943296, 2012). "In repeated stress stimulation-induced depression rats, EA also increased the number of p-CREB-positive neurons in the hippocampus and restored hippocampal BDNF mRNA expression induced by immobilization stress." (PMID 23198761, 2012). "Our results extend previous studies reporting lower serum BDNF levels in patients with major depressive disorder (MDD) relative to healthy controls to a broader, continuous relationship between BDNF levels and depressive symptoms in a community sample." (PMID 21247257, 2012). "Indeed, the finding of increases in the expression of BDNF and of its principal receptor, TrkB, after antidepressant treatment marked the beginning of this line of research and of the neurotrophic hypothesis of depression." (PMID 22654714, 2011). "The presence in the gastrointestinal tract of non-pathogenic bacteria such as Bifidobacteria appear to attenuate an exaggerated stress response, and maintain levels of brain derived neurotrophic factor (BDNF), a neuropeptide known to be low in depression." (PMID 21281494, 2011). "For some protein analytes, the observed change is clearly more marked in one of the disease groups, such as in the case of BDNF and EGF for schizophrenia and insulin for depression." (PMID 20161799, 2010). "In attempt to better understand the neurobiological basis of childhood depression, we explored, in the main study, monoamine and DHEA levels in the limbic system, and BDNF levels in the hippocampus." (PMID 21152205, 2009). "Research has clarified the mysteries behind the BDNF and cAMP-CREB neurotrophic systems and has led us to a new way in understanding the depressive disorder simultaneously providing new targets for drug action." (PMID 19506722, 2008). "Similar to NK-1 receptor and BDNF gene expression, CFA diminished hippocampal p-CREB levels, a phenomenon reminiscent of that previously reported during stress and depression, possibly by triggering intracellular events common to both types of stimuli." (PMID 17974009, 2007). "Anti-inflammatory Lipopolysaccharide (LPS)-induced depression models demonstrated that XYW restored 5-HT levels and reduced indoleamine 2,3-dioxygenase (IDO) expression by activating the NGF/BDNF-TrkA/TrkB-CREB signaling pathway, thereby alleviating neuroinflammation and promoting neuronal survival." (PMID 41535967, 2026). "Although non-significant, the observed trend toward increased BDNF expression aligns with prior reports demonstrating metformin-induced upregulation of BDNF in models of depression and cognitive impairment." (PMID 41578026, 2026).
depression (continued). "Likely, due to the decreased BDNF, depressed mood and increased anxiety, not necessarily reaching the level of clinical depression, are frequently experienced during the pregnancy and postpartum." (PMID 40855004, 2026). "In vivo, a lipopolysaccharide (LPS)-induced mouse model of depression was established to assess the effects of WIS32 intervention on behavioral phenotypes, hippocampal neurochemicals (5-HT and BDNF), and serum pro-inflammatory cytokines (TNF-α, IL-1β, and IL-6)." (PMID 42238885, 2026). "Interestingly, enhancing pro-BDNF signalling in the ACC reduced chronic unpredictable mild stress (CUMS)-induced anxiety- and depression-like behaviours, revealing a unique role of BDNF in emotional–affective behaviours." (PMID 41283278, 2025). "Changes in its activity may affect the BDNF and CREB signaling pathways, mediating the onset of depression, but the specific mechanisms and pathways remain to be further studied." (PMID 40699781, 2025). "The link between BDNF and depression is strong, as postmortem reports have found decreased BDNF gene expression in the brains of people with depression symptoms compared with those of non-depressed individuals." (PMID 40943216, 2025). "The mechanisms by which the intestinal microbiome could impact in the pathophysiology of depression through diet, are mainly related to tryptophan metabolism, HPA axis and brain-derived neutrophic factor (BDNF)." (PMID 39928205, 2025). "Serum brain-derived neurotrophic factor (BDNF) was significantly lower in AECOPD patients with depression compared to their non-depressed counterparts (median: 0.13 vs. 0.24 ng/mL, p < 0.001; d = −1.82)." (PMID 40823578, 2025). "In the present review, a large preventive study conducted among community-dwelling adults aged ≥60 years found that a dose of 2000 IU/day for two years, combined with omega-3 fatty acids, did not reduce the incidence of depression or alter BDNF." (PMID 40871684, 2025). "The strongly positive correlation between hippocampal uPA levels and BDNF, together with the negative correlation between uPA mRNA and anxiety/depression parameters, further supports uPA’s involvement in mood regulation." (PMID 40725146, 2025). "BAs modulate depression pathogenesis through FXR, LXRs, and TGR5 receptors, orchestrating neuroinflammation (via NF-κB/NLRP3 suppression), gut microbiota metabolism (via GLP-1/FGF19 regulation), and neural plasticity (via BDNF/CREB activation)." (PMID 40362260, 2025). "Decreased serum BDNF levels can lead to hippocampal volume reduction, weakening of long-term synaptic potentiation (LTP), and cognitive and emotional deficits reflecting clinical depression symptoms." (PMID 41155506, 2025). "For example, high-frequency rTMS (>5 Hz) enhances the excitability of the DLPFC, promotes glutamatergic neurotransmission and the release of brain-derived neurotrophic factor (BDNF), which improves the symptoms of depression and accelerates the recovery of cognitive function." (PMID 40255888, 2025). "Among studies utilizing stress-based depression models (RS, CRS, and CUS), four targeted the cerebral cortex (l-PLC, PFC, vmPFC, and mPFC), revealing effects on various molecules, such as BDNF, ERK, and mTORC1." (PMID 41154223, 2025). "It has been shown that aerobic exercise increases the ratio of BDNF/proBDNF in the ischaemic hippocampus of rats, and that the balance between BDNF/proBDNF plays a key role in dendritic spine plasticity, which positively affects depression in stroke patients." (PMID 40837062, 2025). "In contrast, another SNP within the BDNF gene, C270T, does not appear to contribute significantly to depression in AD." (PMID 40529210, 2025). "In genetically susceptible models of treatment-resistant depression, SAHA inhibits HDAC2, restores histone acetylation and BDNF levels, and reverses antidepressant non-responsiveness." (PMID 41589304, 2025).